YTHDC2 (YTH N6-methyladenosine RNA binding protein C2)
Diseases named in the same sentence as YTHDC2 in open-access papers (continued):
Sharing a sentence is not in itself a finding about the gene and the disease.
tumor (continued). "We used TISIDB database to show the correlation between YTHDC2 expression and molecular subtypes or immune subtypes across TCGA tumours." (PMID 34312987, 2021). "As a result, we observed that YTHDC2 expressed significantly differently in cancers compared with normal tissues and was down‐regulated in most tumours." (PMID 34312987, 2021). "The mRNA expression of YTHDC2 in stage IV tumor tissues in the TCGA LUSC cohort was significantly lower than that in stage I." (PMID 34326699, 2021). "The present IHC results showed decreased YTHDC2 protein expression in tumor tissues with larger diameters (maximum diameter ≥5 cm), or at advanced T stages (T3 and T4) or pathological stages." (PMID 34326699, 2021). "Although YTHDC2 was unable to stop lung tumorigenesis, the tumor occurrence time was delayed, the overwhelming lung tumor burden was significantly suppressed, and the survival time was longer in KPYWT mice than in KPE mice and KPYΔYTH mice." (PMID 33232910, 2021). "In tumor immunity, YTHDC1, YTHDC2 and ALKBH5 were the most correlated regulatory factors of m6A with immune cell subtypes, and YTHDC1 and YTHDC2 were positively correlated with the selected anti-tumor immune genes." (PMID 34737950, 2021). "The results showed that YTHDC2 expression was closely related to tumour purity in 17 types of cancers." (PMID 34312987, 2021). "YTH domain proteins, including YTHDF1, YTHDF2, YTHDF3, YTDHDC1 and YTHDC2, are the most reported m6A readers and promote the degradation of m6A modified mRNA and tumor progression." (PMID 34295828, 2021). "The expression of m6A regulators with CNV amplification was significantly increased in CC samples compared to normal control samples, such as HNRNPA2B1, IGF2BP1, KIAA1429, and YTHDF1, while METTL14 and YTHDC2 were markedly decreased in the tumor specimens." (PMID 33500720, 2021). "Through this study, we found that YTHDC2 is a tumor suppressor gene with high expression in normal tissues and low expression in tumor tissues through IHC analysis." (PMID 33304653, 2020). "Through this study, we found that YTHDC2 is a tumor suppressor gene with high expression in normal tissues and low expression in tumor tissues." (PMID 33304653, 2020). "Five m6A-related genes (ZC3H13, METTL14, YTHDF2, YTHDF3 and HNRNPA2B1) showed significantly downregulated in tumor tissue, while seven regulators (YTHDC2, FTO, WTAP, METTL3, ALKBH5, RBM15 and KIAA1429) was remarkably upregulated in ccRCC." (PMID 32419773, 2020). "YTHDC2 was highly expressed in female patients and showed a significant relationship with tumor progression." (PMID 32596399, 2020). "The correlations between YTHDC2 and immune infiltration was investigated via Tumor Immune Estimation Resource (TIMER) and Gene Expression Profiling Interactive Analysis (GEPIA)." (PMID 33304653, 2020). "YTHDC2 knockout significantly reduces tumor size and lung metastatic nodules in gastric cancer." (PMID 40986143, 2025). "These differentially expressed mRNAs and the enriched pathways seem to have little relevance to the YTHDC2-mediated alterations in tumor cell stemness, indicating YTHDC2 may exert its function by regulating protein levels." (PMID 41145440, 2025). "IHC staining showed decreased Ki67 level in footpad tumor tissue with YTHDC2 overexpression." (PMID 41145440, 2025). "Furthermore, we detected the cancer stemness biomarkers in T24 xenograft tumors using IHC, which showed reduced CD133 levels in YTHDC2-overexpressing tumor tissues compared to controls." (PMID 41145440, 2025). "In addition to its research in tumors, the role of YTHDC2 in non-tumor diseases has also attracted the attention of researchers in recent years." (PMID 38790013, 2024). "Since we confirmed that YTHDC2 has an effect on the content of exosome in the tumor microenvironment, we next explored whether the discovered YTHDC2 target genes have the function for regulating exosome content." (PMID 39303913, 2024).
tumor (continued). "Knockdown YTHDC2 could enhance cell growth while elevated YTHDC2 expression could suppress cell proliferation, suggesting that YTHDC2 acts as a tumor suppressor in ESCC." (PMID 37598390, 2023). "Downregulation of the YTHDC2 gene can significantly inhibit the translation of tumor metastasis-related genes, such as hypoxia-inducible factor-1alpha (HIF-1α), and the high expression of this molecule is positively correlated with tumor stage and colon cancer metastasis." (PMID 35614935, 2022). "We found that the YTHDC2 expression level was positively correlated with the tumor stage." (PMID 36245989, 2022). "Given the crucial role played by YTHDC2 in tumor immunity, we thoroughly investigated if YTHDC2 expression could predict immunotherapeutic responses." (PMID 35692505, 2022). "In the proliferation experiment, it was found that the low expression of YTHDC2 significantly promoted the growth of cells, suggesting that YTHDC2 may play a role as a tumor suppressor in ESCC." (PMID 34376206, 2021). "In these tumours, YTHDC2 regulates the expression of tumour promoter genes such as HIF1A." (PMID 33461542, 2021). "The result suggests that YTHDC2 may have an important influence on the immune infiltration in most malignant tumours." (PMID 34312987, 2021). "In light of increasing concern of pan‐cancer genetic analysis, which will be beneficial to assess diagnostic and clinical prognostic values of genes on the whole level, we explored YTHDC2 expression in pan‐cancer to further identify the influence of YTHDC2 on tumour promotion and suppression." (PMID 34312987, 2021). "Overall survival was much shorter among acinar LUAD patients with YTHDC2low compared to those without this expression pattern, further demonstrating that YTHDC2 suppression might be especially important for tumor progression of acinar LUAD." (PMID 33232910, 2021). "Therefore, elevating the levels of YTHDC2 was shown to be a promising strategy in LUAD to induce ferroptosis by selectively inhibiting the expression of both subunits of system Xc− in tumor cells." (PMID 34926310, 2021). "Meanwhile, METTL3, and YTHDC2 were suppressed in tumor samples." (PMID 33748145, 2021). "While METTL14 and YTHDC2 functioned as tumor suppressors in KIRC." (PMID 33718187, 2021). "Among them, YTHDC2 had negative associations with tumour purity in seven cancer types, including BRCA‐Basal, READ, COAD, KIRC, HNSC‐HPVneg, LUAD, together with OV." (PMID 34312987, 2021). "Importantly, YTHDC2 functions as a tumor suppressor through the CYLD/NF-κB signaling pathway, which is mediated by m6A modification." (PMID 34326699, 2021). "This study found that YTHDC2 could act as an independent gene as a HNSCC prognostic marker, and provided a potential relationship between YTHDC2 and the interaction of tumor immune infiltration of HNSCC." (PMID 33304653, 2020). "In the absence of diagnostic characteristics, YTHDC2 was then found to be associated with tumor stage." (PMID 32398949, 2020). "However, the mice with YTHDC2 shRNA transduced cells had slow growth, smaller tumor volumes, and less weight than the control tumor after irradiation treatment." (PMID 32850334, 2020). "We found that the copy number loss of ZC3H13, FTO, YTHDC2, WTAP and ALKBH5 decreased the protein expression in tumor samples, and meanwhile, patients with amplification of IGF2BP3, HNRNPA2B1 and IGF2BP2 presented higher expression level of these three proteins than normal tissues." (PMID 32710725, 2020). "We suggest that the ubiquitin-mediated proteolysis affected by YTHDF3 and YTHDC2 may play a crucial role in tumor progression." (PMID 32596399, 2020). "Moreover, YTHDC2 may serve as a tumor suppressor via the m6A-mediated CYLD lysine 63 deubiquitinase/NF-κB regulatory signaling pathway." (PMID 36581942, 2022). "We further investigated whether YTHDC2 is a tumor suppressor in human LUAD cells." (PMID 33232910, 2021).
tumor (continued). "Additionally, the differences in mRNA levels of METTL3, FTO, and YTHDC2 in the studied cell lines indicate that its expression may vary depending on the tumor localization." (PMID 34207099, 2021). "In addition, YTHDC2 was identified to play an important role in tumour cell immune infiltration." (PMID 34312987, 2021). "Thus, YTHDC2 exerts a tumor suppressive function in LUAD via its m6A reading domain." (PMID 33232910, 2021). "Additionally, YTHDC2 was notably correlated with tumour immune infiltration." (PMID 34312987, 2021). "Thus, research on the value of YTHDC2 in immune infiltration from a distinct immune subtype in individual tumours may give assistance to provide new thinking of tumour immunotherapy." (PMID 34312987, 2021). "These indicated that YTHDC2 might be the potential tumor suppressor gene." (PMID 34497675, 2021). "We performed IHC analysis to confirm whether YTHDC2 was relatively low expressed in tumor tissues, and the result showed the protein expression of YTHDC2 in HNSCC tissue were down-regulated compared with normal tissues, which was consistent with the previous database." (PMID 33304653, 2020). "However, the regulatory mechanism of YTHDC2 on tumor behavior is still poorly understood." (PMID 32500031, 2020). "Functional assays demonstrated that METTL16 and YTHDC2 (an m6A reader) collaboratively enhanced MROH8 mRNA stability, thereby inhibiting CAPN2 expression and reducing tumor proliferation and metastasis (P<0.001)." (PMID 39434688, 2024). "The results showed that the expressions of YTHDC2, OAS1, and IFIT2 were all reduced in tumor tissues, whereas the expression of RAB5A was increased in tumor tissues." (PMID 39303913, 2024). "YTHDC2 serves as a prognostic marker for HNSCC and interacts with immune infiltration of HNSCC tumours." (PMID 39135292, 2024). "Immunohistochemical images showed the expression levels of RBM15, VIRMA, YTHDC2, YTHDF2, METTL14, and IGF2BP2 proteins in tumor tissues." (PMID 36791151, 2023). "After further screening, we evaluated the relationship between expression of FMR1, LRPPRC, RBMX, YTHDC2, IGF2BP1 and clinical parameters, including stage, T (tumor infiltrating), N (lymphatic metastasis) and M (distant metastasis) in CRC." (PMID 37194014, 2023). "We evaluated the relationship between expression patterns of RBMX, FMR1, LRPPRC, YTHDC2, IGF2BP1 and clinical parameters, including stage, T (tumor infiltration), N (lymphatic metastasis), M (distant metastasis) in CRC." (PMID 37194014, 2023). "METTL3, METTL14, METTL16, YTHDC1, YTHDC2, and ZC3H13 expression levels were significantly greater in tumor tissues (p < 0.05)." (PMID 36091006, 2022). "Blue background indicated the most significant genes down-regulated in tumor tissues, including YTHDC1, YTHDC2, METTL16, and FTO." (PMID 35581263, 2022). "We found that METTL3, RBM15B, YTHDC2, YTHDF2, and HNRNPA2B1 were indeed highly expressed in the tumor samples." (PMID 34336856, 2021). "Specifically, YTHDF1, IGF2BP2, KIAA1429, RBM15, IGF2BP1, ZC3H13, and METTL3 were significantly up-regulated in tumor tissues by unpaired T-tests (P < 0.05), while ALKBH5, YTHDC2, and METTL14 were significantly down-regulated (P < 0.01)." (PMID 34149792, 2021). "We displayed YTHDC2 expression in normal tissues from GTEX database, the different expression levels in TCGA tumours and adjacent normal tissues from TIMER, and the distribution of YTHDC2 expression in tumours with the data of the GTEX database as controls." (PMID 34312987, 2021). "HNRNPC and YTHDF1 were significantly upregulated in tumor tissues compared with corresponding normal tissues, while ZC3H13, YTHDC2 and METTL14 notably decreased." (PMID 34395102, 2021). "Comparisons between adjacent normal and tumor samples identified seven down-regulated (METTL14, WTAP, YTHDC1, YTHDC2, ALKBH5, FTO, and YTHDF2) and one up-regulated (YTHDF1) regulators." (PMID 32500031, 2020).
tumor (continued). "The most significant positive correlation exists in the writers and the readers' groups, which is consistent with the fact that the expression levels of KIAA1429, YTHDC2, and RBM15 are highly expressed in LUAD tumor tissues." (PMID 32258108, 2020). "Of course, the increase of exosome content caused by YTHDC2 knockdown promoted the malignant phenotype of LUAD cells, which was consistent with our previous finding that the decrease of YTHDC2 promotes the antioxidant capacity of LUAD cells and promotes tumor progression." (PMID 39303913, 2024). "However, another study revealed a significant positive correlation between YTHDC2 expression and CRC tumor staging." (PMID 38790013, 2024). "YTHDC2 also targeted m6A-modified mitochondrial ribosomal protein L12 (MRPL12) mRNA, inhibiting LUAD tumor growth and metastasis, while promoting apoptosis, and ultimately suppressing tumor occurrence." (PMID 38790013, 2024). "Mechanistically, YTHDC2 was shown to bind directly to the mRNA of m6A-modified solute carrier 7A11 (SLC7A11), promoting its decay and thereby inhibiting cysteine uptake, which blocks downstream antioxidant programs, contributing to its anti-tumor activity." (PMID 38790013, 2024). "Numerous studies have underscored the significance of YTHDC2 in human physiology, highlighting its involvement in both tumor progression and non-tumor diseases." (PMID 38790013, 2024). "IGF2BP3 expression increases with tumour grade and correlates with shorter OS.YTHDC2 and IGF2BP3 are negative and positive prognostic factors for OS." (PMID 36831575, 2023). "YTHDC2 expression level is positively correlated with tumor stages in CRC, indicating that YTHDC2 may promote tumor progression." (PMID 37437245, 2023). "Some regulators functioned as tumour suppressors, including METTL5, YTHDC2, and G3BP1." (PMID 34802443, 2021). "Tumor immune-related genes YTHDC1, YTHDC2 and ALKBH5 were found." (PMID 34737950, 2021). "Also, the expression levels of YTHDC2, WTAP, and FTO were markedly lower in tumor tissues (p < 0.05)." (PMID 34277622, 2021). "Most increased regulators in tumor cases compared to normal cases were YTHDF2 (p < 0.001), FTO (p < 0.001), YTHDC1 (p < 0.001), YTHDC2 (p < 0.001), YTHDF1 (p < 0.001), KIAA1429 (p < 0.001), METTL3 (p < 0.010), WTAP (p < 0.001), RBM15 (p < 0.001), HNRNPC (p < 0.001), and ALKBH5 (p = 0.001)." (PMID 32733931, 2020). "Notably, 88.9% (16/18) of these tumor types exhibited reduced YTHDC2 levels in tumor tissues, suggesting a negative correlation between YTHDC2 expression and tumorigenesis." (PMID 41145440, 2025). "However, given that YTHDC2 is a newly discovered m6A binding protein, further studies may be needed to definitively elucidate its role in PTC prognosis and tumor stage." (PMID 40243425, 2025). "Moreover, YTHDC2 modulated LUAD development by regulating the levels of cell division cycle-related protein CDCA4, thereby inhibiting the malignant phenotype and altering the M1/M2 cell ratio in tumor tissue." (PMID 38790013, 2024). "The mRNA expression levels of YTHDC2, YTHDF1, YTHDF3, IGF2BP1, and IGF2BP3 were significantly increased in tumour tissues compared with paired normal breast tissues, while the METTL14, WTAP, FTO, and IGF2BP2 expression levels were significantly decreased in tumour tissues." (PMID 36632454, 2023). "Finally, 8 genes related to anti-tumor immunity were obtained, which were APOL3, CCL5, CD8A, CD8B, CXCL9, GZMA, GZMK and PRF1.We found that the m6A regulatory factors YTHDC1, YTHDC2, and WTAP were positively correlated with m6A, while IGF2BP3 was negatively correlated." (PMID 34737950, 2021). "Therefore, the expression levels of 7 m6A regulators (METTL14, YTHDC2, FTO, ALKBH5, HNRNPA2B1, VIRMA, and RBMX) were lower in both the OC tissues and the high-stage group, indicating their potential function as tumor suppressors in OC tumorigenesis and development." (PMID 34631700, 2021).
tumor (continued). "The role of the YTHDF2 gene in HNSCC has not been explored so far, whereas YTHDC2 was found to be a tumor suppressor with low expression in HNSCC samples, while its upregulation was associated with longer-term survival and the recurrence-free survival of HNSCC patients." (PMID 34207099, 2021). "Firstly, we found that knockdown of YTHDC2 had little effect on tumor growth without radiotherapy." (PMID 32850334, 2020). "YTHDC2 expression is significantly correlated with B cells, CD4+T cells, neutrophils, and dendritic cells, but not with macrophage infiltration in HNSCC, indicating that YTHDC2 may play an important role in immune cells in the tumor microenvironment, especially CD4+T cells and dendritic cells." (PMID 34136491, 2021). "Therefore, we speculate that, the RNA methylation regulated by YTHDC2 and ALKBH5 might regulate tumor proliferation and metastasis through HIF-mediated hypoxic microenvironment response and then affect the prognosis of patients, which would be confirmed in our future research." (PMID 32500031, 2020). "We also constructed a cell-derived xenograft (CDX) model with WT or YTHDC2−/− H1975 cells with or without treatment with GW4869 (exosome biogenesis inhibitor) and found that knockout of YTHDC2 could significantly increase tumor volume and exosome content, and this effect could be reversed by GW4869." (PMID 39303913, 2024).